FTO (FTO alpha-ketoglutarate dependent dioxygenase)
Diseases named in the same sentence as FTO in open-access papers (continued):
Sharing a sentence is not in itself a finding about the gene and the disease.
melanoma (continued). "In melanoma, Yang and colleagues found FTO played a crucial oncogenic role in promoting tumorigenesis and resistance to interferon gamma and anti-PD-1 treatment." (PMID 35961973, 2022). "The eraser enzyme, FTO, promotes melanoma tumorigenesis and resistance to immunotherapy, while decreased FTO expression increased IFNy-induced tumor cell killing and promoted beneficial PD-1 immunotherapy." (PMID 35327975, 2022). "Knocking-out FTO in the melanoma cells through in vitro experiments sensitized to IFN-γ, and increased the immune response of PD-1 inhibitor in mice melanomas." (PMID 36384676, 2022). "Knockout of FTO in melanoma cells induces tumor cells to become sensitive to interferon-gamma (IFNγ) in vitro and promotes a sensitizing response of melanoma cells to anti-PD-1 antibody in mice." (PMID 35311150, 2022). "The knockdown of FTO can increase the sensitivity of melanoma cells to interferon gamma and anti‐PD‐1 therapy." (PMID 34647424, 2022). "Remarkably, inhibition of FTO in melanoma has been found to suppress tumorigenicity and to increase the m6A levels in PD-1, CXCR1, and SOX10, hence enhancing the decay of these m6A-targeted mRNAs by YTHDF2." (PMID 35254013, 2022). "Another study revealed that FTO expression level was increased in human melanoma and contributed to promoting melanoma tumorigenesis and anti-PD-1 resistance." (PMID 35371987, 2022). "Their findings suggest a crucial role of FTO, which increases FTO’s level, decreases response to anti-PD-1 blockade immunotherapy, and enhances tumor growth in melanoma." (PMID 35186927, 2022). "The genetic knockdown of FTO induces the increase of m6A methylation in the critical pro-tumorigenic melanoma cell-intrinsic genes including PD-1, CXCR4, and SOX10, which results in an increased RNA decay through the m6A reader YTHDF2." (PMID 35693795, 2022). "In human melanoma, metabolic starvation stress regulated by autophagy induces the upregulation of FTO, which in turn promotes tumorigenesis." (PMID 36263177, 2022). "A pro-tumorigenic role of FTO was recently discussed in melanoma, illustrating the upregulated FTO levels in human melanoma samples and multiple melanoma cell lines, and reporting that FTO promotes melanoma tumor growth in-vivo." (PMID 35409166, 2022). "The researchers expected that combining FTO inhibitors with anti-PD-1 inhibition would aid in the reduction of treatment resistance in melanoma patients." (PMID 36620557, 2022). "Further research to identify selective FTO inhibitors and more research on their effects in melanoma models are necessary before these results can be adapted to human trials." (PMID 35515106, 2022). "In a study using immunocompetent C57BL/6 mice with B10-F10 melanoma tumors as a model for melanoma resistance to immunotherapies, FTO knockdown restored the efficacy of anti-PD-1 blockade and significantly inhibited tumor growth." (PMID 35515106, 2022). "In melanoma, FTO promoted cell proliferation and overall tumorigenicity by demethylating m6A on melanoma-promoting genes Pdcd1, Cxcr4, and Sox10." (PMID 35350378, 2022). "A high level of FTO was found in human melanoma, and knockdown of FTO increased m6A methylation in PD‐1, CXCR4, and SOX10, causing increased RNA decay through the m6A reader YTHDF2." (PMID 36176733, 2022). "In melanoma, FTO promoted resistance to IFN γ-mediated cell death through m6A demethylation of pro-tumorigenic genes Pdcd-1, Cxcr4, and Sox10." (PMID 35350378, 2022). "FTO inhibitors can be effective in sensitizing melanoma tumor tissues to anti-PD-1 blockade immunotherapy and at the same time in promoting IFN-γ induced killing, which is also essential for the ICB response." (PMID 34526985, 2021). "The researchers proposed that the combination therapy of FTO inhibitors and anti-PD-1 blockade is beneficial to attenuate resistance to immunotherapy in melanoma patients." (PMID 34531875, 2021).
melanoma (continued). "For example, inhibiting FTO sensitizes melanoma cells to anti-PD-1 and interferon gamma (IFNγ) treatment." (PMID 34422815, 2021). "Another study demonstrated that FTO impeded interferon-gamma (IFN-γ)-induced cytotoxicity in melanoma cells in vitro by upregulating PD-1, CXCR4, and SOX10 through suppression of YTHDF2-mediated RNA decay process." (PMID 33500720, 2021). "The collective results from these PD-1 studies have indicated the critical role of melanoma cell-intrinsic FTO in promoting melanoma resistance, such as to anti-PD-1 blockade." (PMID 34105069, 2021). "In keeping with this, FTO knockdown sensitized melanoma cells to IFN-γ and anti-PD-1 treatment by increasing YTHDF2-dependent PD-1, CXCR4, and SOX10 RNA decay in mice." (PMID 34616742, 2021). "Knockdown of FTO made melanoma cells more sensitive to interferon gamma (IFN-γ), thereby reducing the resistance to anti-PD-1 therapy in mice in an adaptive immunity-dependent manner." (PMID 34956201, 2021). "Knockout of fat mass and obesity-associated protein (FTO) can increase the m6A methylation of important genes such as PD-1,CXC chemokine receptor 4 (CXCR4) and SRYBox transcription factor 10 (SOX10) in melanoma cells." (PMID 34737950, 2021). "Knockout of FTO in melanoma cells increased the sensitivity of tumor cells to interferon gamma and enhanced the response of mice to anti-PD-1 antibodies." (PMID 34745261, 2021). "In melanoma, we have recently shown that FTO promotes the mRNA stability of the melanoma-promoting genes PDCD1, CXCR4, and SOX1013." (PMID 33846348, 2021). "In a melanoma mouse model treated with anti-PD-1 immunotherapy, knockout of FTO significantly inhibited tumor growth." (PMID 33777035, 2021). "Elsewhere, research into melanoma also unveiled that FTO increased cell proliferation and migration; FTO knockdown decreases the expression of melanoma-related genes via an m6A-YTHDF2-mediated-manner." (PMID 34277426, 2021). "Intriguingly, both “writers” inhibition (METTL3 or METTL14) and “erasers” inhibition (FTO or ALKBH5) are proved to enhance the efficacy of anti-PD-1 blockade even in the same cancer (melanoma)." (PMID 34526985, 2021). "The combination of FTO inhibition and anti-PD-1 blockade reduced the resistance of melanoma to immunotherapy." (PMID 34956201, 2021). "Knockdown of FTO sensitized melanoma cells to interferon gamma and sensitized melanoma to anti-PD-1 treatment in mice, depending on adaptive immunity." (PMID 34804948, 2021). "Knockdown of FTO sensitizes melanoma cells to interferon gamma (IFNγ) and sensitizes melanoma to anti-PD-1 treatment in mice." (PMID 34526985, 2021). "The researchers also found that that m6A mRNA demethylation by FTO increases melanoma growth and decreases response to anti-PD-1 blockade immunotherapy." (PMID 32754191, 2020). "Collectively, these findings suggest that FTO plays an important role in promoting the occurrence of melanoma and anti-PD-1 resistance." (PMID 32398132, 2020). "Not only that soft tissue tumors are controlled epigenetically, but FTO has also been incriminated in the progression of the solid tumor, including melanoma." (PMID 33511112, 2020). "In melanoma, FTO can act as an m6A demethylase to promote melanoma tumorigenesis and anti-PD-1 resistance." (PMID 33015074, 2020). "Yang’s study also demonstrated that knockdown of FTO sensitized melanoma cells to interferon gamma and anti-PD-1 treatments depending on adaptive immunity." (PMID 32299393, 2020). "In melanoma, FTO can impair IFNγ-induced killing via augmenting CXCR4, PD-1 and SOX10 expression via repressing YTHDF2-mediated degradation and suppress response to anti-PD-1 blockade immunotherapy." (PMID 33015074, 2020). "FTO accelerated melanoma tumorigenesis and anti-PD-1 resistance by regulating the expression of critical cell-intrinsic genes in an m6A-YTHDF2 dependent manner." (PMID 33304380, 2020).
melanoma (continued). "The FTO negatively regulates the response to anti-programmed death 1, an immunotherapeutic agent, through the action of melanoma-intrinsic genes including PD-1, C-X-CR-4, and SOX10; those are the major potential gene targets for demethylation by FTO." (PMID 33511112, 2020). "In melanoma, FTO promotes cancer cell growth and suppresses the effects of anti-PD-1 blockade immunotherapy, and inhibition of FTO in glioma suppresses cancer stem cell growth and self-renewal." (PMID 32296573, 2020). "Here we report that the m6A demethylase FTO regulates melanoma growth and mediates melanoma resistance to anti-PD-1 antibody in vitro and in vivo." (PMID 31239444, 2019). "Knockdown of FTO increases m6A methylation in the critical protumorigenic melanoma cell-intrinsic genes including PD-1 (PDCD1), CXCR4, and SOX10, leading to increased RNA decay through the m6A reader YTHDF2." (PMID 31239444, 2019). "We next used both candidate and unbiased screening approaches to determine the potential mRNA targets of FTO in its melanoma-promoting function." (PMID 31239444, 2019). "Consistently we found that IFNγ downregulates FTO in melanoma cells, and FTO mediates resistance to melanoma cell killing by IFNγ through its m6A demethylase activity and downstream targets PD-1 (PDCD-1), CXCR4, and SOX10." (PMID 31239444, 2019). "Further studies are warranted to assess the full mechanism of immune regulation by PD-1 blockade with FTO inhibition in melanoma." (PMID 31239444, 2019). "Here, the authors show that FTO promotes melanoma tumorigenicity and contributes to resistance to anti-PD1 blockade, while FTO inhibition sensitizes melanoma to anti-PD1 blockade." (PMID 31239444, 2019). "Our findings suggest FTO as a critical adaptation mechanism in melanoma cells under metabolic stress." (PMID 31239444, 2019). "Although FTO knockdown inhibits melanoma tumor growth in both immunocompromised and immunocompetent hosts, the response of FTO knockdown cells to anti-PD-1 requires host adaptive immunity." (PMID 31239444, 2019). "To determine the role of FTO in human melanoma, we first analyzed FTO protein levels specifically in the melanocytes of normal human skin and malignant melanoma samples using immunofluorescence." (PMID 31239444, 2019). "Taken together, these results demonstrate a critical role of melanoma cell-intrinsic FTO in promotinging melanoma resistance to anti-PD-1 blockade, suggesting that FTO inhibition can reduce resistance to anti-PD-1 therapy." (PMID 31239444, 2019). "Knockdown of FTO sensitizes melanoma cells to interferon gamma (IFNγ) and sensitizes melanoma to anti-PD-1 treatment in mice, depending on adaptive immunity." (PMID 31239444, 2019). "FTO increases proliferation, migration, and invasion in melanoma cells in vitro and melanoma tumor growth in vivo." (PMID 31239444, 2019). "FTO knockdown increases m6A enrichment in the critical melanoma-promoting genes including PD-1 (PDCD1), CXCR4, and SOX10, and decreases their mRNA stability." (PMID 31239444, 2019). "FTO knockdown did indeed sensitize melanoma cells to IFNγ-induced growth inhibition and cell killing." (PMID 31239444, 2019). "To investigate potential pathways by which FTO is upregulated in melanoma cells, we analyzed the role of metabolic stress, since cancer cells acquire adaptive capabilities to survive and grow under metabolic stress." (PMID 31239444, 2019). "In melanoma, FTO impairs IFNγ-induced killing in melanoma cells in vitro via up-regulating PD-1, CXCR4, and SOX10 through suppressing YTHDF2-mediated-degradation and inhibits response to anti-PD-1 blockade immunotherapy." (PMID 31801551, 2019). "Overall, our findings demonstrate a crucial role of the m6A demethylase FTO in melanoma tumorigenesis and response to immunotherapy." (PMID 31239444, 2019).
melanoma (continued). "Third, we used m6A- seq in combinaton with RNA-seq to identify more than 1000 potential transcriptome-wide m6A-modifiedgene targets for FTO, including the melanoma-promoting genes CXCR4 and SOX10." (PMID 31239444, 2019). "Consistently, blocking IFNγ by anti-IFNγ antibody increased tumor growth of both control and B16F10 melanoma cells with FTO knockdown in C57BL/6 mice." (PMID 31239444, 2019). "FTO (Red) was low in epidermal melanocytes in normal skin (n = 16), while it was significantly increased in all diagnoses of melanoma, including metastasis (n = 64), primary melanoma (n = 36), and melanoma at stages I–IV (n = 65)." (PMID 31239444, 2019). "In summary, we have demonstrated that FTO inhibition suppresses melanoma tumorigenicity and the expression of melanoma cell-intrinsic genes PD-1 (PDCD1), CXCR4, and SOX10, at least partially through YTHDF2-mediated mRNA decay." (PMID 31239444, 2019). "It is possible that, at least in part, IFNγ exerts its cytotoxic effect by inhibiting FTO in melanoma cells." (PMID 31239444, 2019). "To elucidate the role of FTO in melanoma pathogenesis in vivo, we performed xenograft and syngeneic melanoma tumorigenesis assays." (PMID 31239444, 2019). "The FTO and PLA2G6 genes, which show significant associations with melanoma in both species, have been more classically studied in the light of metabolism and adiposity traits." (PMID 29963229, 2018). "As a pro-tumorigenic factor, FTO is up-regulated in melanoma as well." (PMID 40483535, 2025). "Conversely, in melanoma cells, PD-1 expression is positively regulated by FTO." (PMID 40176140, 2025). "Combining FTO inhibition with a PD-1 blockade has the potential to enhance melanoma immunotherapy." (PMID 39980685, 2025). "Thus, the role of m6A eraser (FTO) in melanoma, and its use in restoring sensitivity to immune therapies is still under evaluation." (PMID 40427015, 2025). "Targeting regulators like METTL3, METTL14, the IGF2BP family, ALKBH5, or FTO can enhance the efficacy of PD-1 blockade therapy in renal clear cell carcinoma, colorectal cancer, melanoma, NSCLC, breast cancer, hepatocellular carcinoma, and intrahepatic cholangiocarcinoma." (PMID 39372415, 2024). "In skin cancers like melanoma and squamous cell carcinoma, aberrant m6A modifications are linked to tumorigenesis and progression, with dysregulation of regulators such as METTL3 and FTO enhancing tumor cell proliferation and invasion." (PMID 39472463, 2024). "In addition, FTO removes m6A tumor-suppressive m6A modifications in melanoma, thus playing a tumorigenic role." (PMID 39468015, 2024). "In melanoma, metabolic stress upregulates FTO via autophagy and the NF-κB pathway." (PMID 39468015, 2024). "In addition, reducing the expression of FTO promotes the expression level of PD-1, thereby improving melanoma resistance to immunotherapy." (PMID 39033180, 2024). "FTO knockdown increased the sensitivity of melanoma cells to anti-PD-1 therapy." (PMID 37264402, 2023). "Knockdown of FTO elevated the m6A level in transcripts of several critical melanoma-promoting genes, including PD-1, C-X-C motif chemokine receptor 4 (CXCR4), and SOX10, then accelerated RNA decay mediated by YTHDF2, restoring IFN-γ response in vitro and sensitizing anti-PD-1 treatment in vivo." (PMID 36810281, 2023). "It is reported that FTO could promote melanoma tumorigenesis and decrease its response to immunotherapy in melanoma." (PMID 37598390, 2023). "By targeting these processes, the FTO inhibitor Dac51 effectively suppresses melanoma." (PMID 37582735, 2023). "In human melanoma, FTO is upregulated, and PD-1 is a potential FTO target gene." (PMID 39872957, 2023). "FTO knockout increased m6A methylation of genes including PD-1 (programmed cell death protein 1), CXCR4 (C-X-C motif chemokine receptor), and SOX10 (Sry-related HMG-box-10) in melanoma cells and thereby enhanced the susceptibility to interferon therapy." (PMID 37124930, 2023).
melanoma (continued). "FTO was supposed to negatively regulate anti-PD-1 immunotherapy response in melanoma." (PMID 36810281, 2023). "FTO also serves as an oncogene in other tumours, such as melanoma and breast cancer." (PMID 36859310, 2023). "Similarly, in melanoma, FTO knockdown increased tumor cell sensitivity to anti-PD-1 treatment by IFNγ in mice." (PMID 36960074, 2023). "Interestingly, they found that the knockdown of the autophagy key genes ATG5 or ATG7 significantly reduced HBSS-induced FTO, suggesting that autophagy-induced melanoma tumorigenesis, which was promoted by the increased FTO." (PMID 36632456, 2023). "FTO has a comparable antitumor effect on melanoma as a factor in anti-PD-1 resistance." (PMID 36620557, 2022). "Therefore, the deficiency of FTO can help to sensitize melanoma cells to IFN-γ stimulation and increase the efficacy of anti-PD-1 immunotherapy in mice bearing melanoma xenograft tumor, which is associated with the activation of adaptive immunity." (PMID 35693795, 2022). "FTO promotes melanoma tumorigenesis and inhibits anti-PD-1 blockade immunotherapy." (PMID 36071523, 2022). "The reported cascade of events relating FTO upregulation to melanoma tumorigenesis is suggested to be initiated by metabolic stress, a metabolic challenge faced by tumor cells, which in turn induces FTO upregulation as a means of melanoma adaptation to metabolic challenges." (PMID 35409166, 2022). "Knockdown of FTO increases m6A methylation of PD-1 in melanoma cells, while deletion of ALKBH5 (the ‘eraser’ of m6A) enriches the 3’UTR region of PD-L1 mRNA with m6A modifications, thereby promoting the degradation of PD-1 and PD-L1 in a YTHDF2-dependent manner." (PMID 35309316, 2022). "In melanoma, combining FTO inhibition with blocking the PD-1/PD-L1 checkpoint may relieve the resistance to immunotherapy." (PMID 36517820, 2022). "Knockdown of FTO could sensitize melanoma cells to interferon gamma and anti-PD-1 treatment in mice." (PMID 35371987, 2022). "Furthermore, in melanoma cells, overexpression of FTO promoted migration and overall tumorigenicity in an m6A-dependent manner, while knockdown of FTO inhibited migration." (PMID 35350378, 2022). "In addition, FTO suppression increased the m6A methylation of critical pro-tumorigenic melanoma cell-intrinsic genes (programmed cell death-1, PD-1; C-X-C motif chemokine receptor 4, CXCR4; and sex-determining region Y-box 10, SOX10)." (PMID 35628623, 2022). "The inactivation of FTO reduced the drug resistance to anti-PD-1 treatment of melanoma in mice." (PMID 35628623, 2022). "Additionally, FTO depletion sensitizes melanoma cells to interferon-gamma (IFNγ) and sensitizes melanoma to anti-PD-1 treatment." (PMID 35186927, 2022). "Furthermore, FTO knockdown alleviated melanoma resistance to anti-PD-1 treatment; suggesting that FTO inhibition in combination with anti-PD-1 immunotherapy is a promising anti-melanoma therapy." (PMID 35409166, 2022). "Moreover, knockdown of alpha-ketoglutarate-dependent dioxygenase (FTO) in tumor cells sensitized to interferon gamma (IFN-γ) in vitro enhances the PD-1 treatment in murine melanoma." (PMID 35677634, 2022). "Consequently, FTO depletion enhanced the response of mouse melanoma cells to IFN‐γ and anti‐PD‐1 therapies." (PMID 36176733, 2022). "The combination of m6A demethylase FTO inhibition with anti-PD-1 blockade may reduce the resistance to immunotherapy in melanoma." (PMID 35186927, 2022). "In melanoma, starvation triggers autophagy and the NF-kB pathway, which in turn activates FTO." (PMID 34315538, 2021). "Accumulating evidence has shown that FTO contributes to the development and progression of cancers, including endometrial cancer, ovarian cancer, pancreatic cancer, lung squamous cell carcinoma, melanoma and acute myeloid leukemia." (PMID 34076564, 2021).